IGF1R (insulin like growth factor 1 receptor)
Diseases named in the same sentence as IGF1R in open-access papers (continued):
Sharing a sentence is not in itself a finding about the gene and the disease.
adrenocortical carcinoma (21 papers, 2008 to 2025). "Our findings demonstrate that metformin inhibits proliferation in the adrenocortical cancer cell model H295R in association with a decreased expression of the IGF2/IGF-1R system." (PMID 27391065, 2016). "Linsitinib, an IGF1R inhibitor currently in Phase III clinical trials for adrenocortical carcinoma, emerged as the top hit associated with enhanced activity in REST-high cell lines." (PMID 27698411, 2016). "The results turned out that knock-down of BTRC abolished the down-regulation of HuR, CDK6, and IGF1R expression upon enhanced expression of ASB16-AS1 in adrenocortical carcinoma cells." (PMID 33219221, 2020). "Several studies have shown the involvement of IGF1/IGF1R and mTOR pathways in the pathogenesis of adrenocortical carcinoma." (PMID 29507530, 2018). "We demonstrated amplification and overexpression of IGF1R gene in only one adrenocortical carcinoma, suggesting that these combined events are uncommon." (PMID 25110710, 2014). "Amplification of IGF1R was detected in only one adrenocortical carcinoma (Weiss score 7) that was diagnosed in a woman who had an endocrine hyperfunction that was characterized by hypercortisolism and hyperandrogenism." (PMID 25110710, 2014). "IGF1R blockade with linsitinib was previously found to be ineffective in adrenocortical carcinoma." (PMID 36809604, 2023). "Additionally, a selective IGF1R kinase inhibitor exhibited antitumor effects in adult and pediatric adrenocortical tumor cell lines, suggesting that IGF1R inhibitors represent a promising therapy for human adrenocortical carcinoma." (PMID 25110710, 2014). "In addition, the adrenocortical carcinoma with IGF1R amplification did not harbor the p.R337H mutation in blood or tumor tissue DNA (data not shown)." (PMID 25110710, 2014). "The insulin-like growth factor 2 (IGF2) is overexpressed in 90% of adrenocortical carcinomas (ACC) and promotes cell proliferation via IGF1R and isoform A of insulin receptor (IRA)." (PMID 40038716, 2025). "We knocked down the expression of HuR in adrenocortical carcinoma cells and the results showed that inhibition of HuR reduced the stability of CDK6 and IGF1R mRNAs." (PMID 33219221, 2020). "We then found that IGF1R and CDK6 are regulated by ASB16-AS1 in adrenocortical carcinoma cells by transcriptome RNA sequencing." (PMID 33219221, 2020). "We then found that IGF1R and CDK6 were up-regulated upon knockdown of ASB16-AS1 in adrenocortical carcinoma cells." (PMID 33219221, 2020). "Collectively, these data indicate that ASB16-AS1 regulates expression of IGF1R and CDK6 in adrenocortical carcinoma cells." (PMID 33219221, 2020). "We have previously demonstrated that estrogen receptor (ER) alpha (ESR1) increases proliferation of adrenocortical carcinoma (ACC) through both an estrogen-dependent and -independent (induced by IGF-II/IGF1R pathways) manner." (PMID 26131713, 2015). "IGF1R amplification was detected using MLPA and confirmed using real time PCR in an adrenocortical carcinoma that was diagnosed in a 46-year-old female patient with Cushing's syndrome associated with clinical virilization." (PMID 25110710, 2014). "Recent reports have also shown that sirtinol inhibits SIRT1, downregulates several proteins such as ERα, CCND1, and IGF1R to interfere with the E2/ERα and IGF1R pathways and activate apoptosis, thereby reducing the growth of H295R and SW13 adrenocortical carcinoma cells." (PMID 39479446, 2024). "Our study found that ASB16-AS1 inhibits IGF1R and CDK6 in adrenocortical carcinoma, modulating of their levels may be developed to treat this type of carcinoma." (PMID 33219221, 2020). "Finally, IGF-1R might not be a major driver of adrenocortical carcinoma." (PMID 27102148, 2016).
microcephaly (20 papers, 2008 to 2025). A congenital or acquired developmental disorder in which the circumference of the head is smaller than normal for the person's age and sex. "Global IGF-1 or its receptor (IGF-1R) deficiency typically leads to lethality, and in the case of survival, individuals present with microcephaly and suppressed somatic growth." (PMID 38247874, 2024). "This condition was in line with the clinical criteria that were proposed for heterozygous IGF1R mutations or terminal chromosome 15q deletions, including a small body size and head circumference at birth, short stature, and microcephaly later in childhood." (PMID 34322776, 2021). "The heterozygous mutations of the IGF1R gene lead to intrauterine and postnatal growth retardation and microcephaly." (PMID 34322776, 2021). "Patients with IGF-1R mutation show growth retardation, microcephaly, feeding problems and mild intellectual impairment." (PMID 31101650, 2019). "In humans, both homozygous and heterozygous mutations of the IGF-1R have been described and several developmental defects are consistently found in these patients, including microcephaly and cortical layer disorganization." (PMID 28794445, 2017). "As previously reported, multiple family members may show similar features of growth retardation and microcephaly, and molecular analysis of the affected family members has revealed similar IGF1R mutations." (PMID 28720553, 2017). "Similarly, a second patient born SGA who suffered from postnatal growth delay, microcephaly, and mild mental retardation was evaluated for IGF-1R mutations." (PMID 22587301, 2012). "Germline mutations in IGF1R are associated with pre- and post-natal growth retardation and microcephaly and combined investigations of the epigenetic and transcriptional effects of germline SETD2 LoF and codon 1740 mutations could provide candidate genes for aspects of SETD2-associated NDDs." (PMID 37166351, 2023). "In human, mutations in IGF-1 and/or IGF1R lead to reduced binding of the IGF-1 ligand to the IGF1R receptor, resulting in microencephaly." (PMID 38075281, 2023). "Patients with genetic IGF-1R defects, show symptoms (i.e., pre and postnatal growth retardation, microcephaly, cardiac defects and dysmorphic features) that significantly overlap with those presented in various CDG types." (PMID 35211808, 2022). "Several mutations in the IGF1R have been reported to result in common phenotypic features like IUGR, stunted postnatal growth development, and microcephaly." (PMID 22693602, 2012). "Genetic defects in either IGF-1 or IGF-1R that result in SGA size typically correlate with phenotypical features such as microcephaly and mental retardation." (PMID 22587301, 2012). "In contrast, complete absence of IGF-1R in bIGF1RKO−/− mutants resulted in microcephaly, indicative of a neurotrophic role for IGF-1R." (PMID 18959478, 2008). "Interestingly, both in genetic SRS and in IGF1R cases, the percentage of postnatal absolute microcephaly is significantly increased if compared to IC1_LoM (60-80% vs 18%)." (PMID 39412159, 2025). "Furthermore, genetic SRS and IGF1R patients show postnatal microcephaly more frequently than IC1_LoM SRS." (PMID 39412159, 2025). "Therefore, their decreased affinity to IGF1R may result in phenotypes such as severe intrauterine and postnatal growth retardation, microcephaly, and sensorineural deafness." (PMID 35907924, 2022). "For example, the majority of CDG patients analyzed in the present study showed growth failure and microcephaly, which are also clinical hallmarks of IGF-1/IGF-1R defects." (PMID 35211808, 2022). "However, microcephaly is the clinical feature which allows the discrimination between SRS and the majority of its differential diagnosis, in our cohort IGF1R disturbances and MGS1." (PMID 33482836, 2021).
microcephaly (continued). "Because patients 5 and 6 did not have relative microcephaly and lipoatrophy/hyperextensibility of joints, respectively, which are characteristic clinical features of IGF1R abnormality and SHORT syndrome, clinical diagnosis of those in both patients might be difficult." (PMID 32546215, 2020).
thyroid-associated ophthalmopathy (20 papers, 2018 to 2025). "In the context of targeting fibroblasts, IGF-1R inhibitors have been extensively studied as therapeutic agents for autoimmune diseases, particularly active thyroid-associated ophthalmopathy (TAO)." (PMID 41509070, 2025). "On the other hand, IGF1R inhibitor alleviated pain behaviors, attenuated hyperalgesia, and teprotumumab (IGF1R inhibitor) reduced proptosis, the Clinical Activity Score and improved quality of life in patients with thyroid associate ophthalmopathy." (PMID 37242543, 2023). "Graves' ophthalmopathy (GO) is one of GD extra-thyroidal manifestations associated with the presence of TSAb, and insulin-like growth factor-1 receptor (IGF-1R) autoantibodies, that interact with orbital fibroblasts." (PMID 33935970, 2021). "An insulin-like growth factor-1 receptor inhibitor, teprotumumab-trbw is used to treat thyroid eye disease also known as Graves’ orbitopathy or thyroid-associated ophthalmopathy." (PMID 33864098, 2021). "It reports on the insulin-like growth factor-1 receptor (IGF-1R) as novel autoantigen in GD and associated Graves orbitopathy (GO)." (PMID 32929476, 2020). "The insulin-like growth factor 1 receptor (IGF1R) is an RTK shown to have crosstalk with TSHR in brow fat and orbital fat of patients with thyroid-associated ophthalmopathy." (PMID 34524974, 2021). "Most recently, teprotumumab, an IGF-1R inhibitor, has shown promising therapeutic value for reducing proptosis in Graves’ ophthalmopathy, which is the most prominent extrathyroidal manifestation of GD." (PMID 34484118, 2021). "Natural autoantibodies to the IGF1 receptor (IGF1R-aAb) have been described in relation to Graves’ ophthalmopathy." (PMID 31940750, 2020). "Additionally, insulin-like growth factor-1 receptor (IGF-1R) is overexpressed in the orbital fibroblast (OF) and lymphocyte of patients with Graves’ ophthalmopathy." (PMID 39872310, 2024). "In addition, IGF-1R inhibitor showed marked improvement in thyroid-associated ophthalmopathy in humans even though two other human studies did not demonstrate benefits from IGF-1 treatment." (PMID 37242543, 2023). "At present, most of the targeted imaging based on insulin-like growth factor 1 receptor (IGF-1R) is for tumor research, and there is no IGF-1R-targeted imaging for Graves’ ophthalmopathy(GO)." (PMID 39920417, 2025).
metabolic syndrome (19 papers, 2012 to 2025). A cluster of metabolic risk factors for CARDIOVASCULAR DISEASES and TYPE 2 DIABETES MELLITUS. "Additionally, the lipodystrophic syndrome observed in Aα4KO mice is similar to the metabolic syndrome associated with generalized lipodystrophy in humans and mice with adipocyte-specific deletion of IR and IGF1R." (PMID 36241662, 2022). "The altered expression of hsa-miR-199a-3p influences energy homeostasis and metabolic adaptation via the suppression of IGF1R (insulin-like growth factor 1 receptor) and HIF1A (hypoxia-inducible factor 1-alpha), which are associated with metabolic syndrome." (PMID 40699679, 2025). "Comorbidities such as diabetes, abdominal obesity, dyslipidemia, glucose intolerance, and metabolic syndrome (MetS) are higher in the African American community and lead to upregulation of the IGF-1R signaling pathway." (PMID 35008602, 2021). "•Deletion of IR/IGF1R in adipocytes leads to lipodystrophy and metabolic syndrome." (PMID 35964946, 2022). "The interrupted or less efficient cardiac IGF-1R signaling in GMP could either explain or be consistent with their physical dwarfism and their higher susceptibility to metabolic syndrome and H-ARS." (PMID 32708958, 2020). "Finally, this work demonstrated that lncRNA XIST alleviates hepatic IR via regulating the miR‐182‐5p/IGF‐1R axis, which could be the promising therapeutic target of IR‐related diseases such as T2D and metabolic syndrome." (PMID 38018594, 2023). "Finally, eleven CpG sites were associated with metabolic syndrome: cg08862778 (MTOR), cg11322849 (INS), cg07199894 (ULK1), cg11658986-cg04149773 (ADCY6), cg14862787-11301281 (CREB5), cg14844401-cg20300093 (ADCY5), cg01284192 (IGF1R) and cg08128650 (RELA)." (PMID 30926763, 2019).
squamous cell carcinoma (19 papers, 2008 to 2025). A carcinoma arising from squamous epithelial cells. "We found that membranous and cytoplasmic IGF-1R expressions were significantly associated with squamous cell carcinoma (SCC) in both of the TMAs." (PMID 25944691, 2015). "IGF-1R overexpression was strongly associated with squamous cell carcinoma, as 79.2% of squamous cell lung cancer displayed high IGF-1R staining versus 35.4% of adenocarcinomas (p<0.0001)." (PMID 19806209, 2009). "In the current study, we have identified PINCH-1 as a positive regulator of IGF-1R expression in A431 squamous carcinoma cells in culture as well as skin tumors in mice." (PMID 35401828, 2022). "Insulin‐like growth factor‐1 receptor (IGF‐1R) is a cell membrane receptor involved in cell proliferation is expressed in the head and squamous cell carcinoma." (PMID 35307810, 2022). "Depletion of PINCH-1 from HaCaT keratinocytes in culture and normal epidermis in mice, like that from A431 squamous carcinoma cells and chemical carcinogen-induced skin tumors in mice, also reduced the IGF-1R level." (PMID 35401828, 2022). "In advanced NSCLC, IGF1R expression is common, particularly in squamous carcinoma, but it has not shown a significant association with overall survival, suggesting that IGF1R gain or expression alone is not a prognostic marker." (PMID 41303594, 2025). "miR-143-3p was shown to downregulate IGF1R in rheumatoid arthritis and in squamous cell carcinoma." (PMID 38539461, 2024). "The findings that ablation of PINCH-1 from A431 epidermoid carcinoma cells inhibited IGF-1R expression, cell proliferation and survival prompted us to test whether PINCH-1 plays a role in regulation of skin tumor growth in vivo." (PMID 35401828, 2022). "In a randomized phase II study of patients with advanced treatment-naïve NSCLC, disease in those with squamous cell carcinoma responded to the combination of paclitaxel, carboplatin and an anti-IGF-1R antibody (CP-751,871) better than those with other histological subtypes." (PMID 19806209, 2009). "High-grade expression of IGF-1R and elevated preoperative squamous cell carcinoma antigen level were independent predictors of both death and recurrence, and combination of both factors could further help identify the subgroup of patients at higher death risk." (PMID 18781172, 2008). "Interestingly, IGF-1R overexpression has been shown in squamous cell carcinoma and recent studies suggested that it could serve as a predictive biomarker of response to anti-IGF-1R antibody, such as R1507 or figitumumab." (PMID 24212944, 2011). "The results showed that high membranous IGF1R expression was predictive of poor progression-free survival (PFS) in adenocarcinoma, but had better PFS in squamous cell carcinoma." (PMID 27213344, 2016). "Patients with squamous cell carcinoma overexpress IGF-1R more frequently than the patients with a nonsquamous histology." (PMID 25925741, 2015).
Wilms tumor (19 papers, 2013 to 2024). An embryonal neoplasm characterized by the presence of epithelial, mesenchymal, and blastema components. "Increased gene copy number of IGF-1R has been associated with recurrence, and in general with worse outcomes in Wilms tumor." (PMID 23383402, 2013). "Overexpression of IGF1R was associated with poor outcome in Wilms’ tumors, whereas the inhibition of IGF1R activity could decrease cancer malignancy." (PMID 31035970, 2019). "It is unknown if AYA patients with Wilms tumors are more likely to have IGF1R mutations than other patient populations or if AYA patients may benefit from IGF1-targeted therapies." (PMID 26328274, 2015). "A high level of Erk1/2 phosphorylation was also observed in the Wt1-Igf2 Wilms tumor mouse model and was postulated to be due to Igf2 signaling through IGF1R activation." (PMID 33379206, 2020). "The role of IGF-1R signaling in the pathogenesis of Wilms tumor was proposed at least as early as 1989, when an anti-IGF-1R antibody slowed tumor growth in an in vivo model." (PMID 23383402, 2013). "However, the roles of TGFBRI and IGF1R in the progress of nephroblastoma require further investigation." (PMID 31035970, 2019). "In this case, the tumor was established by orthotopically injecting Wilms tumor cells with elevated IGF1R signaling but without a WT1 mutation in the kidney of mice." (PMID 27213811, 2016). "In the present study, we proved that TGFBR I and IGF1R are direct target of mi-140-5p, whereas the data further indicated that overexpression of miR-140-5p could modulate their expression and the proliferation and metastasis of nephroblastoma cells." (PMID 31035970, 2019). "miRNA-140-5p expression was downregulated in Wilms’ tumor tissues, and miR-140-5p could regulate Wilms’ tumor progression via the IGF-1R/ AKT and TGFBRI/SMAD2/3 pathways and that it might have tumor suppressive functions with regard to Wilms’ tumor progression and metastasis." (PMID 31035970, 2019). "We demonstrated that miRNA-140-5p participates in the progression of Wilms’ tumor by targeting the TGFBRI/SMAD2/3 and the IGF-1R/AKT signaling pathways." (PMID 31035970, 2019). "We also found that IGF1R and TGFBRI expression in nephroblastoma tissue were higher than that of adjacent normal tissues." (PMID 31035970, 2019). "In the present study, we demonstrated that IGF-1R and TGFBRI were highly expressed in Wilms’ tumor tissues and that they participated in Wilms’ tumor progression." (PMID 31035970, 2019). "Our data suggested that miR-140-5p regulated Wilms’ tumor progression and TGFBRI/SMAD2/3 and IGF-1R/AKT signaling pathways participate in this process." (PMID 31035970, 2019). "Most recently, a mouse xenograft model in which cells from a Wilms tumor cell line were grown orthotopically within mouse kidney was used to show that AEW541, an IGF-1R inhibitor, reduced tumor growth." (PMID 23383402, 2013). "Also, agents targeting the IGF-1R/AKT and TGFBRI/SMAD2/3 signaling pathways have demonstrated anti-tumor activity in preclinical studies and are being evaluated in clinical trials for their efficacy and safety in Wilms tumor patients." (PMID 39062028, 2024). "The lack of therapeutic efficacy of U0126 in this Wilms tumor model and only a transient decrease of glucolytic activity could be explained, at least in part, by continuing IGF2-induced signaling from IGF1R through the PI3K-AKT-mTOR pathway, bypassing the block in MAPK signaling." (PMID 22875335, 2013).